IFNG (interferon gamma)
Diseases named in the same sentence as IFNG in open-access papers (continued):
Sharing a sentence is not in itself a finding about the gene and the disease.
infection (continued). "We demonstrate that the suppression of interferon gamma signaling, which was previously shown to be mediated by the effector TgIST, also occurs in the context of prolonged infection with bradyzoites and that TgIST export is a process that occurs beyond the early stages of host cell infection." (PMID 32156805, 2020). "Infection with M51R resulted in a significant (p < 0.05) increase of mRNAs associated with type 1 IFNs including IFNβ1 and different subtypes of IFNα, as well as type II IFN (IFNγ)." (PMID 32587580, 2020). "Melanomacrophage centers (MMCs), pigmented phagocytic cells (melanin) that act as a rapid response to the presence of an infection, and cytokine levels, such as interleukin-1 (IL-1), IL-6, and interferon-gamma (IFN-γ) are also considered markers of the immune response in fish." (PMID 32605275, 2020). "During infection, key mammalian innate immune response factors (e.g., interferon gamma, tumor necrosis factor alpha, interleukin 1 [IL-1], and IL-6) have evolved to modulate iron metabolism in order to inhibit overall iron release and thus starve invading pathogens for the molecule." (PMID 32699121, 2020). "In contrast, after aerosol infection with Mtb, IL-6-/- mice exhibit only an initial increase in bacterial burdens accompanied by a delayed IFNγ induction; however, these mice are eventually able to contain mycobacterial growth and to mount a protective memory response to secondary infection." (PMID 33334075, 2020). "High iron also reduced serum iron-binding capacity, apolipoprotein, and immunoglobin A. The RNA-sequencing analysis revealed that iron changed colonic transcript profile, such as interferon gamma-signal transducer and activator of transcription two-based anti-infection gene network." (PMID 33392192, 2020). "Although the innate and adaptive immune effector cells can directly destroy the infected liver cells, much of the antiviral ability of these cells results from production of antiviral cytokines at the site of infection, such as interferon-gamma (IFN-γ) and tumor necrosis factor-alpha (TNF-α)." (PMID 32664850, 2020). "However, during the course of infection, the frequency of IFNγ-secreting CD4+ T cells was similar in both groups." (PMID 33375150, 2020). "After a 2 h infection period, residual extracellular Cn were removed by washing and the cells were cultured for a further 24 h in growth medium containing either IFNγ to maintain the M1 polarization state or IL-4 to repolarize to M2, with the growth medium and cytokines replaced at 6 h intervals." (PMID 32857777, 2020). "Previous analyses of MAP whole cell lysate stimulated immune responses at 6–15 months post-infection have consistently identified one or more of IFNG, IL12, TNFA, and/or IL17A (either transcript or protein) as up-regulated in either CPPs or the draining MLN cells." (PMID 32547548, 2020). "IFNγ is another critical cytokine in controlling the infection of M. tuberculosis." (PMID 32582206, 2020). "However, this view is currently under debate due to a poor correlation between the levels of IFNγ and the degree of protection against the infection." (PMID 33334075, 2020). "However, during the course of infection myeloid cells activated by IFNγ or other cytokines most likely are involved in protection against MAP." (PMID 32408806, 2020). "CD8+ T cell IFNγ production is the major mediator of this infection." (PMID 32733814, 2020). "Interestingly, Gutzeit and colleagues reported the secretion of signature Th1 cytokines (IFNγ and IL-12) was enhanced following infection of MDDCs with (v-OKA) but blocked by a VZV clinical isolate." (PMID 32038653, 2020). "Consequently, while infections seem to be responsible for reduced frequencies of IFNγ+TNFα+ co-expressing CD4+ T-cells in the first 2 years of life, an increase of triple producers is merely due to development." (PMID 32849561, 2020).
infection (continued). "During acute T. gondii infection NK cells and ILC1 are known to produce IFNγ in an IL-12 dependent manner We have recently demonstrated that after vaccination, NK cells respond a second time to help control challenge infection by producing IFNγ in an IL-12 and IL-23 dependent manner." (PMID 32733814, 2020). "In the late stage of infection, the abundance of msa transcripts of R. salmoninarum in the surviving fish from both groups induced a chronic pro-inflammatory response based on the significant overexpression of the transcripts of IL-8 and IFNγ." (PMID 32695119, 2020). "Infiltrating T cells and NK cells are the main sources of IFNγ during infection." (PMID 32133008, 2020). "We reasoned that since IFNγ-stimulated BMDMs are refractory to the parasite, Toxoplasma-induced genes that support the intracellular parasite lifestyle are likely to be targeted and reversed when BMDMs are pre-stimulated with IFNγ prior to infection." (PMID 33014886, 2020). "This residual NK cell population might be responsible for the production of IFNγ after infection with HAdV-C6, which was at par with that in the liver of wild-type hamsters." (PMID 32651192, 2020). "Thus, the interferon gamma mRNA levels in peripheral blood leukocytes were determined by reverse transcription-quantitative PCR (qRT-PCR), following the time course of infection." (PMID 32098825, 2020). "We also evaluated whether IFNγ-activated macrophages clear the B. cenocepacia intracellular infection by determining bacterial colony forming units (CFUs) at 1 and 24 h post-infection." (PMID 32873215, 2020). "Interestingly, while IFNγ levels remain fairly steady, IP-10 levels increase over the course of infection." (PMID 33378361, 2020). "Levels of interferon-gamma (IFNγ) production were high in mice treated with morphine before infection (just like the sulfadiazine plus pyrimethamine) compared with those in the no drug group, whereas levels of interleukin 4 (IL-4) productions were low across all treatment groups." (PMID 32398975, 2020). "Interestingly, the frequency of IFNγ+ NK cells continued to decrease from weeks 5 to 7 post infection." (PMID 32733814, 2020). "Importantly, the abundance of AIM2, whose expression was upregulated by IFNγ, was unchanged during the course of Tg infection." (PMID 31268602, 2019). "In this screen, IFNγ-induced stress was achieved by pre-treating HeLa cells for 24 h with 10 ng/mL of IFNγ followed by infection for 24 h in presence of the stressor, while recovery was assessed 24 h after cells were washed and replenished with tryptophan-free media supplemented with indole." (PMID 31024512, 2019). "However, after challenge infection with T. britovi, significantly higher levels of IFNγ were found in the rTbCLP+adjuvant group than the others." (PMID 31681308, 2019). "Indeed, IFNγ‐primed MDMs infected with Tg displayed marked apoptosis within 3 h post‐infection, which preceded PI uptake induced by post‐apoptotic necrotic membrane damage (Silva, 2010)." (PMID 31268602, 2019). "Infection of TAP1−/− mice results in reduced CD4 T cell IFNγ production." (PMID 30873151, 2019). "At day 14 after infection, the levels of IFNγ, and MIP1β in lung homogenates were higher in naïve and in RA treated unvaccinated mice as compared to either vaccine subunits or BCG vaccinated mice, reflecting the higher bacterial load found in these groups of mice." (PMID 31130946, 2019). "IFNγ is a potent pro-inflammatory cytokine secreted by activated lymphocytes during infection." (PMID 31461509, 2019). "The top regulated biological terms for both GH and IFNγ treated cells include response to bacterium, response to virus, response to other organism, defense response and phagocytosis, consistent with a role for GH in immune responses to infections." (PMID 31852980, 2019). "In humans, NK cells are thought to be some of the first cells to produce IFNγ during infection." (PMID 30873151, 2019).
infection (continued). "To begin to define the requirements for vaccine induced immunity we conducted vaccination studies in T cell or IFNγ-deficient mouse strains lacking the key players we identified for resolution of the infection." (PMID 31231045, 2019). "Although NK cell IFNγ production is important for reducing parasite numbers early during infection, the IFNγ producing liver ILCs could be ILC1." (PMID 30873151, 2019). "Indeed, like natural Tg infection, STAg transfection triggered IFNγ‐dependent apoptosis in ΔCASP1 cells." (PMID 31268602, 2019). "We recently showed that the IFNγ dose-dependent restriction of Tg-infection depends on cell type, with epithelial cells displaying a sharp parasiticidal effect, in contrast to macrophages, fibroblasts, and endothelial cells demonstrating a dose-dependent response." (PMID 31830133, 2019). "Infection of mice with other hypervirulent Mtb strains, such as thosebelonging to the W-Beijing lineage, also results in a poor protective Th1-drivenimmune response distinguished by the low and temporal expression of IFNγ, TNFα, andiNOS." (PMID 31411311, 2019). "Additionally, IFNγ gene expression was observed 4 days post sub-lethal infection in pulmonary T cells." (PMID 31443439, 2019). "Furthermore, we found that the expression levels of CD107a/b and IFNγ in transferred P14 cells were positively correlated with TCF1 expression at day 15 post infection with Cl13." (PMID 30814995, 2019). "H-1PV infection alone and in combination with both checkpoint inhibitors caused strong activation of CTLs, which was reflected by an increased number of CD8+GranB+ cells and increased release of granzyme B, IFNγ, and TNFα." (PMID 31192129, 2019). "However, the addition of exogenous IFNG significantly inhibited the production of IL10 protein in response to infection with both M. bovis strains." (PMID 31527895, 2019). "Interestingly, SID1 requirement for in vivo colonization is the most obvious at 15 days post-infection perhaps due to IFNγ production by T cells, which restricts iron availability and peaks at 14 days post-infection." (PMID 31560240, 2019). "This suggests that GH has functions that at least partially overlap with IFNγ and may impact the ability of the host to respond to an infection." (PMID 31852980, 2019). "Interestingly, the frequencies of IFNγ-secreting and degranulating uneducated and educated NK cells was significantly increased upon iNKT cell activation prior to infection, as compared to both untreated but infected and untreated uninfected mice." (PMID 31704965, 2019). "YFP‐caspase‐4C258S translocation could be detected on 37% of SCVs within 2 h of infection in Dox‐ and IFNγ‐primed cells." (PMID 31268602, 2019). "The natural infection or exposure to B. anthracis induces the expansion and differentiation of specific T-cells, with growing evidence that cellular immune responses involving IFNγ-producing CD4+ T-cells contribute significantly to protective immunity." (PMID 31213220, 2019). "Other authors have found elevated IFNγ in non-infected multiparous women which is associated with the absence of infection and conclude an important role of IFNγ in protecting against infection." (PMID 30930847, 2019). "In fact, subclinical infection is the result of an effective T helper 1 (Th1) cellular immunity, with the activation of macrophages by interferon-gamma (IFN-γ) and tumor necrosis factor-alpha (TNF-α) and the elimination of intracellular amastigotes via the l-arginine nitric oxide pathway." (PMID 31806038, 2019). "However, although IL10 siRNA resulted in elevated TNF and IFNG mRNA levels during G18 infection, they remained significantly lower than that measured during AF2122/97 infection." (PMID 31527895, 2019). "Interestingly, these mice also exhibited significantly elevated pulmonary IFNγ concentrations after infection with PR8 or CAL09." (PMID 31744208, 2019). "IFNγ was induced by Ma.24 infection for 37.3‐fold at 12 hours." (PMID 31596045, 2019).
infection (continued). "In order to determine whether NK cell-derived IL-10 can regulate T cell activation during infection, we measured the IFNγ production by T cells." (PMID 31803193, 2019). "A 10-fold increase in TNFα was observed when the child cleared infection, but the IFNγ secretion was either unchanged or decreased with increase in age indicating that the NK cells were either not activated or inhibited by certain receptors, which subsequently supressed IFNγ synthesis." (PMID 31396204, 2019). "Endogenous anti-IFNγ antibodies are associated with infections with tuberculosis, non-tuberculous mycobacteria (NTM), Cryptococcus neoformans, Penicillium marfannei, and species of non–typhoidal Salmonella." (PMID 31892200, 2019). "Given that the genital tract microbiota contains indole-producing bacteria, it has been proposed that C. trachomatis genital serovars may rely on their tryptophan synthase to evade the antimicrobial effects triggered by IFNγ during in vivo infections." (PMID 31024512, 2019). "After challenge, the IFNγ-response got more robust in vaccinated animals (booster effect) while non-vaccinated animals developed a cell mediated response at levels indicative of a primary response to PRRSv infection." (PMID 31577832, 2019). "Alternatively, the decline in IFNγ-producing T cells in blood upon infection of control and vaccine 1 group might hint at their migration to infected tissues." (PMID 31620134, 2019). "Besides, treatment with antibodies that selectively deplete Marginal Zone B cells rendered mice more capable of inducing enhanced IFNγ responses and clearing the infection." (PMID 30881362, 2019). "However, once an infection has been established (after 5 days), there is an increase in production of interferon gamma (IFN-γ), the most relevant cytokine for mounting an efficient immune response against Brucella sp." (PMID 30804100, 2019). "In addition, at 28 weeks’ post-infection, human proinflammatory cytokines such as interferon gamma (IFN-γ), monocyte chemoattractant protein 1 (MCP-1) and interleukin 18 (IL-18) were significantly increased in the plasma of HIL mice." (PMID 31213010, 2019). "The ability of IFNγ to dampen myeloid cell IFNGR1 may also be important to ensure dampening of macrophage responsiveness in the context of infections where pathogen burden is insufficiently high to drive a strong type I IFN response." (PMID 31585982, 2019). "Similar to the luminescence data, a decrease in C. burnetii GE values was observed in the IFNγ-treated cells compared to untreated cells at 4-days post-infection and tryptophan supplementation of cells treated with IFNγ resulted in a significant increase in C. burnetii GE values by d7 pi." (PMID 31461509, 2019). "Toxoplasma gondii induces a strong CD4 T cell response that is a major source of IFNγ during both acute, as well as chronic infection, and is similar to what has been observed in other infections." (PMID 31119107, 2019). "IFNγ‐signaling deficiency in mice results in extreme susceptibility to infection by the eukaryotic pathogen Tg and the Gram‐negative bacterial pathogen Salmonella enterica Typhimurium (STm), among others." (PMID 31268602, 2019). "Consistent with a possible shift from acute to chronic infection, we observed production of IFNγ and IL-17 at later time points post-infection, which could represent S. aureus-specific adaptive Th1/Th17 responses." (PMID 30978245, 2019). "Furthermore, for biphasic profiles, antiviral cytokines were initially (i.e. first week post infection) dominated by IFNα and then by IFNγ, whereas IFNγ always dominated for uniphasic profiles." (PMID 30696429, 2019). "On average 5.6 times more IL1B mRNA (p < 0.001), 5.2 times more IL6 mRNA (p < 0.001), 4.3 times more TNF mRNA (p < 0.001) and 48.5 times more IFNG mRNA (p < 0.001) were produced by bMDM pre-treated with NTC siRNA in response to AF2122/97 infection than G18 infection." (PMID 31527895, 2019).
infection (continued). "Furthermore, the absence of NK cells resulted in reduced B. pertussis-specific IFNγ secretion and an increase in IL-5 secretion by spleen cells isolated 14 days after infection." (PMID 31507615, 2019). "The efficacy of IL-21 and IFNγ in modulating CD8 TRM differentiation may vary based on the duration of infection and the cells in the surrounding tissue parenchyma." (PMID 31514273, 2019). "One of our hypotheses associated to a direct role of IL17F in TB, implies that different amounts of this cytokine could influence the levels of IL17A and IFNG secreted by HD and TB, affecting the onset of the infection." (PMID 31616423, 2019). "However, mice that received all three infections were able to produce IFNg in response to different viral peptides, with the highest level of IFNg production in response to pooled peptides." (PMID 29963060, 2018). "Enhancement of IFNγ responses in the 6mo-cases could result from infection-induced pre-activation of NK cells, cytokine-induced memory-like NK cells generation, and/or help from CD4+ T cells." (PMID 29520269, 2018). "Of note is the fact that IFNα, although impacted by both ART and ART+PH-797804, remained with IFNγ the most abundant measured cytokine when compared to pre-infection values, despite undetectable viremia in some of the animals, suggesting an ongoing stimulation of innate responses." (PMID 30161247, 2018). "Whereas mnd2tg mice (C57BL/6 background) displayed comparable baseline Ly49H-expressing NK1.1+CD3− frequencies and comparable post-infection spleen weights, they had significantly higher IFNγ-producing Ly49H+ NK cell frequencies relative to control littermates." (PMID 29855523, 2018). "Alterations in IFNγ and PPARγ signaling may be a possible mechanism by which M1/M2 macrophage populations are altered in Stat2−/− mice in super-infection." (PMID 30337919, 2018). "However, alteration of the intestinal microbiota reduces the regulatory oversight, allowing for increased IFNγ production, leading to increased mortality from the infection." (PMID 30042764, 2018). "But it still can be speculated that IFNγ and IL-17 may be partially secreted by Vγ6+ T cells apart from Vγ1+ T and Vγ4+ T cells during Cm infection." (PMID 29670466, 2018). "IL-17 induces the expression of pro-inflammatory cytokines and chemokines, such as G-CSF, IL-6 and IL-8, promoting recruitment of neutrophils and granuloma formation, as well as the expression of other chemokines, including CXCL10 that recruits IFNγ producing cells to the site of infection." (PMID 29554138, 2018). "Gene ontology enrichment indicated that multiple vital biological processes are involved in CH60 strain infection, including inflammatory response, cytokine-mediated signaling pathway, defense response to virus, cellular response to interferon gamma, and immune response." (PMID 30197639, 2018). "In acute experimental T. cruzi-infection, IFNγ is essential for parasite control." (PMID 29768622, 2018). "On the other hand, as VIP has anti-inflammatory properties, this may impede the pathogen clearance as it has been demonstrated that for example IFNγ plays a role during clearance of infection." (PMID 30252907, 2018). "Further studies are necessary to determine whether additive/synergistic effects of each infection on IFNγ expression are responsible for the increased disease severity observed in the co-infected mice." (PMID 30467504, 2018). "IL-18 is a potent inducer of IFNγ, a cytokine required to survive infection with B. thailandensis." (PMID 29791511, 2018). "However, the percentage of IFNγ+ Vγ4+ T cells increased rapidly after infection and even reached the peak at day 3 p.i. then restored to the basic level at day 7 p.i.." (PMID 29670466, 2018).